LINC00536 (long independently transcribed non-coding RNA 536)
Gene: Long non-coding RNA gene on chromosome 8 (115,950,511 to 116,451,731, reverse strand). Ensembl gene ENSG00000249917.
Diseases named in the same sentence as LINC00536 in open-access papers:
LINC00536 is named in the same sentence as 4 diseases in open-access papers, as found by Europe PMC text mining. Sharing a sentence is not in itself a finding about the gene and the disease. The quoted sentences say what the papers report.
breast carcinoma (4 papers, 2019 to 2024). "The silencing of LINC00536 inhibits the proliferation, migration, and invasion of breast cancer cells." (PMID 39456830, 2024). "Two intronic AIMs (rs13267382: chr8, LINC00536; rs9952980: chr18, SLC14A2) and two intergenic AIMs (rs10832963: chr11, SPTY2D1 - SRSF3P1; rs11814448: chr10) were also found to be associated with breast cancer in samples of European and Asian ancestry." (PMID 36911410, 2023). "To explore the function of LINC00536 in breast cancer cells, we performed qRT‐PCR in MCF‐7 and BCAP‐37 cells and in the normal breast cell line MCF‐10A." (PMID 30932362, 2019). "Using GraphPad Prism to analyze the expression levels of LINC00536, CDH2, and mir‐204, the results indicated that the expression levels of LINC00536 and CDH2 were increased in breast cancer, while mir‐204 expression was decreased." (PMID 30932362, 2019).
cancer (4 papers, 2018 to 2025). A tumor composed of atypical neoplastic, often pleomorphic cells that invade other tissues. "For example, LINC00536 and EFNA5 were highly expressed in clusters 1 and 10, which represented two sub-clusters of cancer cells." (PMID 38473208, 2024). "So far, no studies have reported any association between LINC00377, LINC00536, LINC01224, and LINC02037, and cancer." (PMID 31850229, 2019). "No study so far has reported any association of LINC00536, AL391421.1 or LINC00491 with cancer." (PMID 30261893, 2018).
LINC00536 also shares sentences with these, for which no sentence is quoted: fibroids (2 papers); tumor (1).